CCND1 (cyclin D1)
Diseases named in the same sentence as CCND1 in open-access papers (continued):
Sharing a sentence is not in itself a finding about the gene and the disease.
prostate carcinoma (continued). "Several studies have confirmed that miR-193a-3p inhibits the growth of gastric and prostate cancer cells by targeting CCND1, but its role in HCC remains unclear." (PMID 32095323, 2020). "LOXL1-AS1 via targeting miR-541-3p and CCND1 could regulate prostate cancer cell proliferation and cell cycle progression." (PMID 33330110, 2020). "In addition, it is also known to play roles in the proliferation and survival of prostate cancer (PC) cells via miR-541-3p and cell cycle gene CCND1 as well as aggressive nature of glioblastoma by activating NF-kB pathway." (PMID 32591022, 2020). "MiR-501-3p by targeting CREPT/CCND1 could restrict prostate cancer growth and increase G0/G1 arrest." (PMID 33330110, 2020). "Furthermore, miR‐16‐5p enhances the radiosensitivity of prostate cancer cells by modulating the cyclin D1/E1‐pRb‐E2F1 signaling pathway." (PMID 31505105, 2019). "It was found that apocynin inhibited cancer cell proliferations via down-regulating cyclin D1, which might be related with NF-κB activation in rat prostate cancer cell lines." (PMID 31551769, 2019). "Since RORα1 reduced the expression of cyclin D1 and c-myc, we examined whether RORα1 could inhibit proliferation through the concomitant reduction of cyclin D1 and c-myc expression in prostate cancer cells." (PMID 30987323, 2019). "LncRNA SNHG7 could accelerate prostate cancer proliferation and cell cycle progression through cyclin D1 by sponging miR-503." (PMID 30103699, 2018). "Western blot analysis demonstrated that TA treatment significantly increased the protein levels of p21WAF1/CIP1 and p18INK4C, while it decreased the protein levels of cyclin D1 (G1 phase positive regulator) in prostate cancer cells when compared to control cells." (PMID 29518944, 2018). "Interestingly, among the several pathways statistically enriched (P ≤ 0.05, Fisher’s test), some genes were involved in Prostate Cancer Signaling, especially Ras, P ten and Cyclin D1." (PMID 29740090, 2018). "Importantly, our present results lend direct support to recent findings implicating WNT5A in the suppression of prostate cancer metastases through a complex network of signaling proteins, including Snail, Cyclin D1 and c-Myc." (PMID 28886116, 2017). "We found that ESM1 knockdown in prostate cancer cells resulted in increased cell proliferation and colony formation ability response evidenced by decreased expression of p21 and increased expression of cyclin D1 in prostate cancer cells." (PMID 28108731, 2017). "A previous study reported that miR-143 inhibits cyclin D1 expression in prostate cancer cell lines." (PMID 28746466, 2017). "Furthermore, the cyclin D1-mediated gene expression signature predicts poor outcome in human prostate cancer." (PMID 29137223, 2017). "Amplification or overexpression of cyclin D1 plays pivotal roles in the development of a subset of human cancers including parathyroid adenoma, breast cancer, colon cancer, lymphoma, melanoma, and prostate cancer." (PMID 26689991, 2016). "Cyclin D1 (CCND1) is overexpressed in many types of human cancer including prostate cancer." (PMID 27186486, 2016). "The cyclin D1 network in prostate cancer antagonizes EMT and enhances cancer stem cell populations." (PMID 27385093, 2016). "Similarly, TMPRSS4 moderately increased DU145 prostate cancer cell proliferation and moderately induced cyclin D1 expression in these cells." (PMID 27385093, 2016). "Nuclear paxillin has also been observed to increase cell proliferation via transcription of Cyclin D1 in prostate cancer cells, by acting as a nuclear scaffold, to promote extracellular-regulated kinase (ERK) phosphorylation of the ETS domain-containing protein (Elk-1)." (PMID 26984511, 2016). "Furthermore, NQO2 was reported to regulate the stability of cyclin D1 in CWR22Rv1 prostate cancer cells by AKT/GSK‐3β signal pathway." (PMID 27165481, 2016). "A higher level of cyclin D1 was found in metastasis of androgen-independent prostate cancer." (PMID 26416244, 2015).
prostate carcinoma (continued). "Taken together, our data demonstrate that miR-193b targets cyclin D1 in prostate cancer." (PMID 26129688, 2015). "Here, our aim was to determine if miR-193b targets cyclin D1 in prostate cancer." (PMID 26129688, 2015). "Our findings suggest that cyclin D1 and Bcl2 expression may be useful as predictive markers of responsiveness of prostate cancer to apigenin therapy." (PMID 26379052, 2015). "We have previously shown that the overexpression of miR-193b reduces the proliferation of prostate cancer cells due to a decreased number of cells in S-phase of the cell cycle 8, suggesting that CCND1 could also be a target for miR-193b in prostate cancer." (PMID 26129688, 2015). "Because cyclin D1 is a suggested target of miR-193b in other cancers, we aimed to study whether it is also a target in prostate cancer." (PMID 26129688, 2015). "Because CCND1 is a suggested target of miR-193b target in hepatocellular and pancreatic carcinoma and melanoma 10,11,14, we aimed to determine if it is also a target in prostate cancer." (PMID 26129688, 2015). "In comparison with quiescent status of prostate cancer cells, we noticed an accumulation in cyclin D1, CDK4, cyclin E and CDK2 together with the expected reappearance of phosphorylated pRb when the quiescent cancer cells were induced to re-enter the cell cycle." (PMID 26416244, 2015). "In conclusion, we expanded previous individually underpowered studies and suggested that no obvious association was found between the CCND1 A870G and prostate cancer susceptibility." (PMID 25888980, 2015). "Alternatively, the loss of miR-193b expression could indicate the sensitivity of prostate cancer cells to cyclin D1 inhibition." (PMID 26129688, 2015). "While not a direct target of phenoxodiol treatment in prostate cancer cells, the role of Cyclin-D1 seems to be tissue and oncogene specific, with Cyclin-D1 linked to activation of the Wnt/β-catenin signalling pathway." (PMID 25400509, 2014). "Cyclin D1 expression may be regulated in prostate cancer as a consequence of AKT-mediated activation leading to overexpression of several key proteins including Cyclin D1, a hypothesis, which is also supported by our data." (PMID 24040362, 2013). "Given its robust modulation of several cellular pathways that are highly relevant to prostate cancer such as AR signaling and the cyclin D1/CDK4/RB axis, we tested whether SMIP004 exhibited anti-prostate cancer activity in murine xenograft models." (PMID 23902736, 2013). "In the TRAMP transgenic mouse model of prostate cancer, treatment with BA (10 mg/kg) inhibited primary tumors, increased apoptosis, decreased angiogenesis and proliferation, and lowered androgen receptor and cyclin D1 protein." (PMID 23424652, 2013). "Since CCND1/2 activity is required for cell cycle G1/S transition, we decided to determine whether ATF3 influences CCND1 expression, which further regulates cellular proliferation of human prostate cancer cells." (PMID 23591848, 2013). "We found that 4HPR impairs DU145 and PC3 prostate cancer cells migration and invasion by down-regulating FAK and AKT activation and by enhancing β-catenin degradation, causing the downregulation of target genes like cyclin D1, survivin and VEGF." (PMID 20537156, 2010). "Since the expression of Ebp1 correlated with prostate cancer progression, we also evaluated whether the expression of Ebp1 correlated with the nuclear expression of Ebp1 regulated proteins (AR, Cyclin D1 & ErbB3) and the proliferation marker Ki67." (PMID 19025630, 2008). "In prostate cancer cells, NFκB may promote cell growth and proliferation by regulating expression of genes such as c-myc, cyclin D1, and IL-6, and inhibit apoptosis through activation of expression of anti-apoptotic genes, such as Bcl-2 and Bcl-XL." (PMID 18226269, 2008).
prostate carcinoma (continued). "The present findings demonstrate that cyclin D1 expression is enhanced in the majority of localised tumours as compared to non-neoplastic epithelia, thus indicating that cyclin D1 is aberrantly regulated in prostate cancer." (PMID 17375037, 2007). "Thus, the data herein confirm that increased cyclin D1 is seen with high frequency in prostate cancer, and is the first to provide a detailed assessment of cyclin D1 localisation patterns and correlates in organ-confined disease." (PMID 17375037, 2007). "Future studies directed at delineating mTOR activation may assist in revealing the mechanism(s) by which cyclin D1 accumulates in prostate cancer." (PMID 17375037, 2007). "In addition to the effects on proliferation, previous data in prostate cancer cell lines suggest that cyclin D1 has specialised roles concerning AR function in the control of prostate cancer cellular function." (PMID 17375037, 2007). "To date, few studies have assessed the role of cyclin D1 in prostate cancer." (PMID 16863592, 2006). "Whether these predictions hold true will require deeper consideration of cyclin D1 isoform expression and/or function during prostate cancer development and progression." (PMID 16863592, 2006). "These collective data indicate that the role of cyclin D1 in prostate cancer is complex, and that alterations in full-length cyclin D1 expression and localization may have both positive and negative effects on tumor growth." (PMID 16863592, 2006). "Furthermore, we observed more compelling results with the eRNA‐QTL in CCND1e, which also exhibited strong colocalization with prostate cancer risk loci, but did not colocalize with the eQTL of CCND1." (PMID 39950845, 2025). "Moreover, the regulation of prostate cancer by PSMC2 may be mediated by Akt/Cyclin D1/CDK6 signaling pathway." (PMID 33902600, 2021). "Moreover, SRSF1 regulates the production of cyclin D1 (CCND1) isoform CCND1b in prostate cancer." (PMID 32106418, 2020). "Thus, Cyclin D1 is a functional target of HNF1B in prostate cancer cells." (PMID 33174391, 2020). "The CCND1 gene, which is directly regulated by the EWS-FLI-1 transcription factor, encodes two alternative transcripts of cyclin D1; the common cyclin D1a isoform and a truncated cyclin D1b variant that promotes cellular transformation and prostate cancer progression." (PMID 30093970, 2018). "Furthermore, cancer stem cell radioresistance has been described in several cancer types including prostate cancer and it will be of interest to test whether silencing cyclin D1 in PCa cells that express stem-like properties improves radiosensitivity." (PMID 26689991, 2016). "Indeed, the AR-mediated mechanisms responsible for cyclin D1 and D2 down-regulation by androgen in HPr-1AR differ from the post-transcriptional mechanism that reportedly increases cyclin D1/2 expression in LNCaP prostate cancer cells." (PMID 26372468, 2015). "Our results suggest that the CCND1 A870G polymorphism might not be a potential candidate for predicting prostate cancer risk, including metastasis risk." (PMID 25888980, 2015). "Thus, inhibition of cyclin D1 and E and cdk2, cdk4 and cdk6 suggests that PM might inhibit proliferation by arresting prostate cancer cells in G1-phase." (PMID 25175770, 2014). "The results of previous studies and of the present study indicate that the inhibition of Akt activation by luteolin may result in the downregulation of Mdm-2 and cyclin D1, which may contribute to the induction of apoptosis and cell cycle arrest in colon and prostate cancer cells." (PMID 22269172, 2012). "Therefore, we examined whether the Akt-GSK-3β-Cyclin D1 pathway was involved in BP-induced degradation of cyclin D1 in prostate cancer cells." (PMID 22470469, 2012). "In PC-3 human prostate cancer cells expression of a fusion protein of GFP with the non-catalytic N-terminus of the phosphatase PP6 (the human ortholog of Sit4) caused a G1 cell cycle arrest with a corresponding reduction in cyclin D1 levels." (PMID 22069692, 2011).
prostate carcinoma (continued). "Similarly in another study, we have demonstrated that inhibition of FOXO transcription factors by shRNA blocked resveratrol-induced upregulation of Bim, TRAIL, DR4, DR5, p27/Kip1 and apoptosis, and resveratrol-induced inhibition of cyclin D1 in prostate cancer cells in vitro." (PMID 21209944, 2010). "Furthermore, lactacystin failed to abolish actinomycin D and lovastatin induced cyclin D1 loss in PC-3-M prostate cancer cells." (PMID 17407548, 2007). "Compared to full-length cyclin D1, the cyclin D1b variant was significantly deficient in its ability to repress AR-dependent expression of the prostate specific antigen (PSA) mRNA expression in prostate cancer cells, a target gene used clinically to monitor prostate growth and progression." (PMID 16863592, 2006). "In prostate cancer, it induces snail family transcriptional repressor 2 (SLUG) and cyclin D1, promoting invasion and proliferation." (PMID 40361374, 2025). "Prostate cancer cells (LNCaP and PC-3) treated with RV showed reduced expression of cyclins D1 and E, CDK4, and cyclin D1/CDK4 kinase activity." (PMID 40732979, 2025). "P21 upregulation in response to PAK6 knockdown also contradicts previous findings in prostate cancer cells, where PAK6 knockdown induced expression of cyclin D1, a proliferation marker negatively regulated by p21, enhancing tumor growth in vitro and in vivo." (PMID 40650306, 2025). "Therefore, we hypothesized that polymorphisms of genes encoded cyclin-dependent kinase 4 and 6 (CDK4 and CDK6), cyclin D1 (CCND1), CDK inhibitors p16INK4a and p15INK4b, as well as the retinoblastoma protein (RB), could modulate prostate cancer risk and influence the corresponding mRNA levels." (PMID 40304827, 2025). "A ginsenoside derivative called 1C was shown to inhibit the Wnt pathway in LNCaP—a prostate cancer cell line—by decreasing the levels of β-catenin and TCF4, as well as target genes CCND1 and c-Myc, blocking its proliferation." (PMID 40427472, 2025). "AR activity in prostate cancer cells has been shown to activate the MAPK pathway as well as Src and to increase levels of cyclin D1 via a PI3K/mTOR-mediated mechanism." (PMID 40075623, 2025). "Bioinformatics analysis showed that MYC gene was highly expressed and CCND1 and MAPK1 were low expressed in prostate cancer tissues." (PMID 39061044, 2024). "miR-541–3p is a tumor suppressor miRNA recognized as a negative regulator of CCND1 through binding to 3 ́UTR of CCND1 and is downregulated in prostate cancer." (PMID 39136001, 2024). "In this regard, five mRNAs (CCND1, LMTK2, FN1, EZH2, and GOLM1) were included in a gene panel for prostate cancer diagnosis and reported as differentially expressed in a Chinese cohort of 281 patients using RT-qPCR from tissue samples." (PMID 39595075, 2024). "The role of CA treatment on proliferative proteins (Cyclin-D1, CDK-2, Cyclin-D2) expression in prostate cancer cells PC-3 was examined by western blotting." (PMID 39574470, 2024). "In enzalutamide-resistant prostate cancer cells, suppression of SLC25A17 led to delayed cell cycle progression and reduced protein expression of Cyclin D1 and CDK6." (PMID 38402166, 2024).
prostate carcinoma (continued). "Recently, other SH2 domain inhibitors (323-1 and 323-2) have been developed and lead to the downregulation of STAT3 downstream genes, like the MCL1 apoptosis regulator (MCL1) and cyclin D1 (CCND1), in DU145 prostate cancer cells." (PMID 38067351, 2023). "The increase in cell proliferation and chronic inflammation of the prostate activate the IL-6/STAT-3/cyclin D1 signaling pathway and play a significant role in the pathological progression of BPH and prostate cancer." (PMID 36601166, 2023). "Our qPCR analysis revealed that treatment of Cur-B modulated the gene expression of cyclin D1, CDK4, and p21 in prostate cancer cells." (PMID 37448964, 2023). "Mechanistic studies showed that Co-Sp reduced the expression of cyclin D1, cyclin E, CDK4, CDK2, MMP-9, MMP-1, and Bcl-2, and increased the expression of p21, cleaved caspase-9, cleaved caspase-3, cleaved PARP, and Bax in prostate cancer cells." (PMID 37313467, 2023). "Ascleposide downregulates the expression of cyclin D1, cyclin A, and CDK4 in a dose-dependent manner, and also downregulaets c-Myc (an early identified oncogenes) in human prostate cancer cells." (PMID 35699421, 2022). "miR-3648 facilitates prostate cancer cell proliferation by inhibiting APC2, which leads to the activation of the Wnt/β-catenin pathway by increasing cyclin D1 and cyclin E1 expression and decreasing p21 expression." (PMID 35037826, 2022). "Our bioinformatics analysis from TCGA dataset showed, for prostate cancer tissues, a positive correlation of mRNA expression of MYH9 with mRNA expression of GSK3β, β-catenin, cyclin D1, c-MYC, vimentin, and N-cadherin." (PMID 35589707, 2022). "Subsequently, upregulation of Cyclin D1 and CDK6 was also partially reversed by MK-2206, which served as an evidence for the involvement of Akt/Cyclin D1/CDK6 pathway in prostate cancer." (PMID 33902600, 2021). "Further, selinexor and analogs demonstrate antitumor effects through modulating the expression of CYCLIN D1 and SURVIVIN in prostate cancer models." (PMID 34206543, 2021). "Cyclin D1 and CDK6, as the other two important regulators in cell cycle and cell proliferation, have been demonstrated to be highly expressed in prostate cancer and have enormous potential in wide various of cancer research and prognosis judgement." (PMID 33902600, 2021). "In prostate cancers, HOXB13 downregulated TCF4 and its responsive genes c-Myc and cyclin D1, subsequently inhibiting cell growth." (PMID 33479226, 2021). "The top 30 protein targets with high frequency were CCND1, EGFR, ESR1, and MYC, which can be used as the potential targets of XHP in the treatment of prostate cancer." (PMID 35342388, 2021). "Among the MTA1-associated genes previously identified by our group from MTA1-ChIP analysis were Cyclin D1 and Notch 2, which were shown to be responsive to Pter treatment and directly regulated by MTA1 in prostate cancer cell lines." (PMID 33255879, 2020). "Low-dose celecoxib combined with exisulind can affect the tumorigenesis of prostate cancer by regulating pathways such as EGFR, Akt, androgen receptor, and cyclin D1." (PMID 32913451, 2020). "Cell cycle related proteins, such as c-Myc, Cyclin D1, and p21, lied downstream of MEK/ERK pathway to mediate IGHG1 regulated prostate cancer." (PMID 31355278, 2019). "In prostate cancer, silencing of LOXL1-AS1 suppressed cell proliferation and arrested cell cycle progression via regulating miR-541-3p and CCND1." (PMID 30944201, 2019). "Silencing of CTBP2 markedly increases apoptosis of prostate cancer cells; decreases the expression of IL-8, AT2R, CCND1, MMP9, MYC, and HSPC111; and reduces tumor growth in mouse xenograft model of human prostate cancer." (PMID 31323811, 2019). "SMAD4 is a key regulator of the TGFβ pathway and a suppressor of prostate tumor progression, whereas cyclin D1 and SPP1 act as mediators of the prostate cancer processes." (PMID 31551414, 2019).